RIPK3 (receptor interacting serine/threonine kinase 3)
Diseases named in the same sentence as RIPK3 in open-access papers (continued):
Sharing a sentence is not in itself a finding about the gene and the disease.
parasitemia (2 papers, 2021 to 2025). "Genetic evidence supports that RIPK3-dependent necroptosis clears viral, bacterial, and parasitic infections that can affect host susceptibility (24, 25, 31, –, 35)." (PMID 33526566, 2021). "To confirm that the reduction of parasitemia with TNF-α and Z-VAD-FMK in the presence of RIPK3 and MLKL was due to necroptosis, we assessed host cell survival during infection by measuring cell membrane integrity." (PMID 41055414, 2025).
pneumococcal infection (2 papers, 2022 to 2024). Infections with bacteria of the species streptococcus pneumoniae. "Necroptosis initiated by RIPK3 plays an indispensable role in host defense against Streptococcus pneumoniae infection, whereas RIPK3 deficiency decreases the bacterial clearance rate and aggravates lung inflammation and tissue damage, resulting in a high risk of mortality." (PMID 38684668, 2024).
prostate adenocarcinoma (2 papers, 2022 to 2023). "In prostate adenocarcinoma (PRAD), both the hormone ER and EMT signaling pathways are activated by MLKL and RIPK3." (PMID 37000317, 2023).
renal carcinoma (2 papers, 2022 to 2025). A carcinoma arising from the epithelium of the renal parenchyma or the renal pelvis. "Moreover, in many renal cancer cell lines and clinical samples, expression of RIPK3 is frequently silenced through promoter methylation or other epigenetic mechanisms, thereby preventing activation of the necroptotic cascade." (PMID 41584840, 2025).
retinal detachment (2 papers, 2019 to 2024). An eye emergency condition which may lead to blindness if left untreated. "In a retinal detachment model, RIPK3 activation triggered necroptosis in photoreceptor cells, while the blockade of RIPK1 or deficiency of RIPK3 markedly abolished this effect." (PMID 39065688, 2024).
serous ovarian cancer (2 papers, 2014 to 2018). "The database cataloged an enrichment for RIPK3 expression in serous ovarian cancer." (PMID 25356865, 2014). "Abundant RIPK3 transcript is common in serous ovarian cancers, suggesting that further evaluation and targeting of this RIPK3-dependent pathway may be of clinical benefit." (PMID 25356865, 2014). "Activation of this death pathway was dependent on the kinase activity of RIPK3, and required RIPK1, both of which we show are frequently expressed in serous ovarian cancer, as well as the cytokine TNFα." (PMID 25356865, 2014). "We found that the expression of RIPK3, but not that of RIPK1, was progressively reduced during xenograft tumor growth in four out of five PDX samples derived from high-grade serous ovarian cancer biopsies." (PMID 30157175, 2018).
Thrombocytopenia (2 papers, 2023 to 2024). A reduction in the number of circulating thrombocytes. "This suggests that the thrombocytopenia observed in Abin1Q478H/Q478H mice is not correlated with RIPK3 or necroptosis." (PMID 38009796, 2024).
varicocele (2 papers, 2023 to 2024). A condition characterized by the dilated tortuous veins of the spermatic cord with a marked left-sided predominance. "For example, varicocele, which causes male infertility, seriously affects semen quality, and the expression of RIPK1 and RIPK3 in the sperm of varicocele patients was significantly increased compared to a control group." (PMID 38762505, 2024). "RIPK1, RIPK3, GSDME and HSP 90 were increased in bilateral varicocele group." (PMID 36819092, 2023). "In our study, we found that RIPK1, RIPK3 and HSP 90 were activated in bilateral varicocele group." (PMID 36819092, 2023).
Yersinia pestis infection (2 papers, 2021 to 2023). "Likewise, Casp8–/–Ripk3–/– mice were shown to be susceptible to a subcutaneous Yersinia pestis infection but resistant against an intratracheal infection with E. coli." (PMID 37080966, 2023).
acute lung injury (1 paper, 2025). A condition of lung damage that is characterized by bilateral pulmonary infiltrates (pulmonary edema) rich in neutrophils, and in the absence of clinical heart failure. "Receptor-interacting protein 3 (Ripk3) plays a crucial part in acute lung injury (ALI) by regulating inflammation-induced endothelial damage in the lung tissue." (PMID 39744171, 2025).
acute-on-chronic liver failure (1 paper, 2020). Acute-on-chronic liver failure (ACLF) is an extreme condition during the natural history of chronic HBV infection, with a relatively high short-term mortality. "The current study was performed to investigate necroptosis by measuring its key regulators; receptor interacting protein kinase 3 (RIPK3) and mixed lineage kinase domain-like (MLKL) in patients with Hepatitis B virus (HBV) related acute-on-chronic liver failure (ACLF)." (PMID 32655398, 2020).
adenoma (1 paper, 2024). A neoplasm arising from the epithelium. "Evaluating the similarities of significantly over-represented proteins in the adenoma and carcinoma cell lines, 226 proteins were identified, of which the most over-represented included proteins involved in signal transduction (NUCB1, ZYK) and apoptosis (RIPK3, CASP8)." (PMID 39462388, 2024).
adenovirus infection (1 paper, 2017). "Our data are also intriguing in that, in the absence of caspase inhibition, knockdown of RIPK3, but not MLKL, partially reduces cytotoxicity, suggesting that there may be other death effector proteins that are activated by RIPK3 in the presence of adenovirus infection." (PMID 29238045, 2017).
alcoholic liver cirrhosis (1 paper, 2018). A disorder of the liver characterized by the presence of fibrotic scar tissue instead of healthy liver tissue. "Recent data suggests that receptor-interacting protein kinase-3- (RIPK3-) mediated necroptosis plays an important role in alcoholic cirrhosis." (PMID 30596105, 2018). "Whether the expression of RIPK3 is related to a poor prognosis in alcoholic cirrhosis is hitherto unknown." (PMID 30596105, 2018). "Furthermore, phospho-mixed lineage kinase-like protein (p-MLKL) a downstream molecule of RIPK3 in necroptosis pathway was also activated in the necrotic area in patients with alcoholic cirrhosis." (PMID 30596105, 2018). "Alcoholic cirrhosis is associated with necrotic hepatocyte cell death, called necroptosis, which is regulated by RIP1-RIP3-MLKL- (mixed lineage kinase domain-like protein-) mediated necrotic cascade, but the role of RIPK1 and RIPK3 in the pathogeneses of alcoholic liver cirrhosis is largely unknown." (PMID 30596105, 2018). "RIPK3 and MPO may serve as potential predictors for poor prognosis in patients with alcoholic cirrhosis." (PMID 30596105, 2018). "The present study demonstrates that RIPK3 and neutrophil infiltration in patients with alcoholic cirrhosis can be used to predict poor disease prognosis based noninvasive predictors MELD and invasive histological scoring systems." (PMID 30596105, 2018). "Importantly, RIPK3 and MPO may act as factors to predict poor outcomes in patients with alcoholic cirrhosis." (PMID 30596105, 2018). "Our study showed that RIPK3 but not RIPK1 was activated in patients with alcoholic cirrhosis." (PMID 30596105, 2018). "Very strong RIPK3 staining but not RIPK1 was found in the necrotic area, indicating that RIPK3, but not RIPK1, was involved in alcoholic liver cirrhosis, consistent with previous studies showing RIPK3 is mediated in the mouse model of ethanol-induced liver injury and progression of ALD patients." (PMID 30596105, 2018). "The patients in our study all had end-stage alcoholic cirrhosis, and the results of our study between the relationship of the AHHS score and clinical parameters, MPO, or RIPK3 were not significant, suggesting the AHHS score may not be suitable for alcoholic cirrhosis." (PMID 30596105, 2018).
alcoholic steatohepatitis (1 paper, 2022). "It has been recently reported that RIPK3-controlled necroptosis is involved in the pathogenesis of alcoholic steatohepatitis and a spontaneous NASH-like syndrome due to loss of hepatic O-GlcNAc transferase (OGT)." (PMID 36107452, 2022).
Ascites (1 paper, 2021). Accumulation of fluid in the peritoneal cavity (between the layers of the peritoneum that lines the abdomen). "Patients with ascites and/or younger patients (>50 years) also had more elevated RIPK3 levels." (PMID 34921136, 2021).
astrocytoma (1 paper, 2021). "Our transcriptomic data of U87MG cells 12 h after LPS stimulation and the TCGA RNASeq dataset of astrocytoma showed upregulation of genes related to inflammasome and ripoptosome pathways, namely MYD88, NLRP3, RIPK1 and RIPK3, and also SRF, JUN and IL1B, the downstream regulated genes." (PMID 33446690, 2021).
Atrophy (1 paper, 2025). Any weakening or degeneration, especially through lack of use. "Apoptosis in PT cells results in tubular atrophy with loss of kidney function, and necroptosis participates in the pathogenesis of DKD via the ubiquitin C-terminal hydrolase L1 (UCHL1)-RIPK1/RIPK3 pathway." (PMID 40722167, 2025).
autoimmune disease (1 paper, 2023). A disorder resulting from loss of function or tissue destruction of an organ or multiple organs, arising from humoral or cellular immune responses of the individual to their own tissue constituents. "Conversely, blockade of T cell necroptosis by RIPK3 inhibitor largely ameliorated the inflammatory damage induced by RPA1 depletion, which further confirm the importance of T cell necroptosis in the pathogenesis of autoimmune disorders." (PMID 36721037, 2023).
bacterial pneumonia (1 paper, 2025). Acute infection of the lung parenchyma caused by bacteria (e.g., Streptococcus pneumoniae, Haemophilus influenzae, Chlamydia pneumoniae, Mycoplasma pneumoniae, and Legionella pneumophila). "In ARDS caused by bacterial pneumonia, components such as LPS can stimulate inflammatory cells (such as macrophages) by releasing cytokines for example TNF-α 42, which can activate Ripk3 via the death receptor pathway when bound to cell surface receptors." (PMID 39744171, 2025).
bladder tumor (1 paper, 2024). "In addition, the expression of FATP2 was up-regulated, while the expression of RIPK3 was down-regulated in bladder tumor tissue." (PMID 38461272, 2024).
bronchopulmonary dysplasia (1 paper, 2025). Bronchopulmonary dysplasia is a chronic respiratory disease that results from complications related to lung injury during the treatment of infant acute respiratory distress syndrome in low-birth-weight premature infants or from abnormal lung development in older infants.
cerebral infarction (1 paper, 2024). An ischemic condition of the brain, producing a persistent focal neurological deficit in the area of distribution of the cerebral arteries. "The content of serum RIPK1 and RIPK3 was gradually elevated with increased cerebral infarction volume and the severity of the disease (p < 0.05)." (PMID 39657719, 2024). "AIS patients in ICU had abnormally elevated content of serum RIPK1 and RIPK3, which was closely related to the volume of cerebral infarction, severity and the prognosis." (PMID 39657719, 2024). "AIS patients in the ICU had abnormally elevated content of serum RIPK1 and RIPK3, which was closely related to the volume of cerebral infarction, severity, and prognosis." (PMID 39657719, 2024). "In general, AIS patients in the ICU had abnormally elevated content of serum RIPK1 and RIPK3, which were closely related to the volume of cerebral infarction, severity, and prognosis." (PMID 39657719, 2024). "In this study, the correlation between RIPK1 and RIPK3 with cerebral infarction volume, severity, and prognosis in AIS patients was explored, aiming to provide new targets for the treatment of AIS and bring better prognosis to patients." (PMID 39657719, 2024). "The pairwise comparison showed that those with different cerebral infarction volumes all had a much higher content of serum RIPK1, RIPK3, and TNF‐α than the control (p < 0.05)." (PMID 39657719, 2024). "Serum RIPK1, RIPK3, and TNF‐α levels between the control group and different cerebral infarction volume groups were compared using ANOVA." (PMID 39657719, 2024). "Comparison of serum RIPK1, RIPK3, and TNF‐α levels in patients with different volumes of cerebral infarction." (PMID 39657719, 2024).
cervical (1 paper, 2015). "Our data suggest that the expression status of RIPK3 might critically influence the outcome of PolyIC-based adjuvant immunotherapeutic approaches in cervical (and potentially other) cancers and should therefore be assessed prior to immunotherapy." (PMID 25888634, 2015).
cervical adenocarcinoma (1 paper, 2015). An adenocarcinoma arising from the cervical epithelium. "Cervical adenocarcinomas displayed broader inter-individual and intra-tumoral heterogeneity with respect to RIPK3 expression." (PMID 25888634, 2015). "The crucial role of RIPK3 was identified by comparing two cervical cell lines with differential DC-stimulatory capacities, the cervical SCC cell line C4-I expressing RIPK3 (as shown in this study) and the HeLa cervical adenocarcinoma cell line, which is known to be devoid of RIPK3 expression." (PMID 25888634, 2015). "Notably, we found an even more heterogeneous RIPK3 expression pattern in cervical adenocarcinomas; we observed highly positive examples, as well as cancers with a high percentage of cells that exhibited no RIPK3 expression, which were therefore judged negative using the IRS score." (PMID 25888634, 2015).
Chronic colitis (1 paper, 2018). A chronic inflammatory disease of the large intestine (colon, cecum and rectum). "To obtain further insight why loss of RIPK3 had not improved the response of ADAM17ex/ex mice to DSS-induced acute and chronic colitis, we performed Western blots for molecular markers of cell death." (PMID 29560122, 2018). "In ADAM17ex/ex mice subjected to chronic colitis, we again detected no signals specific for pRIPK3 and pMLKL despite the clear presence of inactive, unphosphorylated RIPK3 and MLKL in all samples, further supporting our assumption that necroptotic signaling is compromised in ADAM17ex/ex mice." (PMID 29560122, 2018).
chronic liver failure (1 paper, 2023). Liver failure that develops slowly and gradually for some time, possibly for years, often as the result of cirrhosis, or malnutrition. "RIPK3 analysis from hepatocytes of different mouse models of inflammatory, cholestatic injury revealed an association of RIPK3 expression induction in models of chronic liver failure but not during an acute toxic liver insult." (PMID 37072399, 2023).
chronic viral hepatitis (1 paper, 2020). "Other studies have also detected an induction of RIPK3 expression on liver biopsies of patients with chronic viral hepatitis, which was not present at baseline." (PMID 33353156, 2020).
cowpox (1 paper, 2025). A mild, eruptive skin disease of milk cows caused by cowpox virus, with lesions occurring principally on the udder and teats. "Unlike cowpox, which eliminates RIPK3 altogether to prevent necroptosis, O. tsutsugamushi lowers RIPK3 levels and does not trigger necroptotic cell death." (PMID 40430799, 2025).
cryptococcal infection (1 paper, 2017). "Interestingly, the phenotypes that developed in Ripk3−/−Fadd−/− mice mirror many findings in cryptococcosis patients who suffer from IRIS." (PMID 28919893, 2017). "Here, we explored the roles of FADD and RIPK3 in a mouse model of cryptococcal infection and identified previously unknown, critical contributions of these molecules in pulmonary immune responses to cryptococcal infection." (PMID 28919893, 2017). "Our first group of studies elucidated the involvement of both RIPK3 and FADD during cryptococcal infection." (PMID 28919893, 2017). "Using a mouse model of cryptococcal infection, the roles of FADD and RIPK3 in anti-cryptococcal defense were investigated." (PMID 28919893, 2017). "Having demonstrated that RIPK3 and RIPK3/FADD deletions altered inflammatory infiltrate compositions, we further examined the roles of RIPK3 and FADD in pulmonary and systemic cytokine levels during cryptococcal infection." (PMID 28919893, 2017). "Thus, both RIPK3 and FADD significantly contributed fungal containment during pulmonary cryptococcal infection." (PMID 28919893, 2017).
End Stage Liver Disease (1 paper, 2022). Final stage of a liver disease when the liver failure is irreversible and LIVER TRANSPLANTATION is needed. "Predominant cytoplasmic RIPK3 expression was found in cholangiocytes in donor livers with ischemia-reperfusion injury and in patients with end-stage liver diseases." (PMID 34700031, 2022). "We showed that RIPK3 is expressed predominantly in cholangiocytes, rather than hepatocytes, in liver biopsy specimens from patients with end-stage liver diseases and donor livers in liver transplantation." (PMID 34700031, 2022).
endothelial dysfunction (1 paper, 2025). In vascular diseases, endothelial dysfunction is a systemic pathological state of the endothelium (the inner lining of blood vessels) and can be broadly defined as an imbalance between vasodilating and vasoconstricting substances produced by (or acting on) the endothelium. "Ripk3 deletion improved lung tissue morphology, reduced inflammation, oxidative stress and endothelial dysfunction under LPS challenge." (PMID 39744171, 2025).
Enterococcus faecalis infection (1 paper, 2021). A bacterial infection induced by Enterococcus faecalis which is the most prevalent species (along with Enterococcus faecium) cultured from humans, accounting for more than 90% of clinical isolates. "The inhibition of RIPK3 activity suppressed Enterococcus faecalis infection-induced cell death in MG-63 cells." (PMID 34400895, 2021). "Inhibitors of RIPK3 and MLKL suppressed cell death from Enterococcus faecalis infection in MG-63 cells." (PMID 34400895, 2021).
fibrosarcoma (1 paper, 2021). A malignant mesenchymal fibroblastic neoplasm affecting the soft tissue and bone. "Here we report that A179L enhanced TNF-α or TSZ (TNF-α, Smac, and Z-Vad)-induced receptor-interacting protein kinase (RIPK1), RIPK3, and mixed lineage kinase domain like peudokinase (MLKL) phosphorylation in L929 cells, a murine fibrosarcoma cell line." (PMID 34960759, 2021).
Flavivirus Infections (1 paper, 2023). Infections with viruses of the genus FLAVIVIRUS, family FLAVIVIRIDAE. "A potential regulator of neuronal IFN signaling during flavivirus infection is receptor interacting protein kinase-3 (RIPK3)." (PMID 38011306, 2023). "In the setting of neuroinvasive flavivirus infection, neurons employ the immunologic kinase receptor-interacting kinase 3 (RIPK3) to promote an antiviral transcriptional program, independently of the traditional function of this enzyme in promoting necroptotic cell death." (PMID 38011306, 2023).
graft versus host disease (1 paper, 2023). An immune system disorder that occurs after allogeneic hematopoietic stem cell transplant and is a reaction of donor immune cells against host tissues. "In addition, another recent study reported the role of RIPK1/RIPK3-mediated inflammatory cascade of alloreactive T cell responses in promoting graft-versus-host disease (GVHD)." (PMID 36969188, 2023).
H1N1 virus infection (1 paper, 2019). "Mice deficient in RIPK3 (Ripk3−/−) are highly susceptible to PR8/H1N1 virus infection, exhibiting heightened morbidity and mortality." (PMID 31165725, 2019).
head and neck squamous cell carcinoma (1 paper, 2024). A squamous cell carcinoma that arises from any of the following anatomic sites: lip and oral cavity, nasal cavity, paranasal sinuses, pharynx, larynx, and salivary glands. "In head and neck squamous cell carcinoma (HNSCC) patients, the loss of RIPK1 and RIPK3 function caused by promoter hypermethylation is closely related with poor prognoses." (PMID 38799433, 2024).